STAT1 (signal transducer and activator of transcription 1)
Diseases named in the same sentence as STAT1 in open-access papers (continued):
Sharing a sentence is not in itself a finding about the gene and the disease.
tumor (continued). "Our data indicate that STAT1 exerts tumor-suppressive effects in hepatocarcinogenesis through induction of G0/G1 cell cycle arrest and apoptosis, and may provide a basis for the design of new therapies for the intervention of HCC in the clinic." (PMID 26617467, 2015). "Both STAT3 and STAT1 also regulate tumour angiogenesis and metastasis, albeit in opposite ways." (PMID 25880691, 2015). "STAT1 was previously shown to function as a tumor suppressor." (PMID 26075897, 2015). "Given our data indicating that STAT1 functions in the MG microenvironment to regulate growth of the normal epithelium, we performed experiments to assess the effects of this microenvironment on tumor cell growth." (PMID 26075897, 2015). "Overexpression of the IFN/STAT1 pathway is associated with poor prognosis in different types of cancer, and selected against fractionated ionizing radiation (IR) and IFN-resistant phenotype from a radiosensitive parental tumor SCC61." (PMID 26617467, 2015). "Furthermore, although IDO expression depends on IFN-γ in multiple cell types, this is the first demonstration of STAT1 signaling involvement in a tumor cell line." (PMID 24911872, 2014). "CCL2, CXCL1, and IL6, produced by 18Co cells could contribute to increased STAT1 activity in tumor cells." (PMID 24818101, 2014). "With this background, we hypothesize that STAT1 may mediate its tumor suppressor function in ESCC by modulating the expression of these anti-apoptotic proteins and cell-cycle regulators." (PMID 25438156, 2014). "The possible explanations for these rather contradictory findings may be related to the biological heterogeneity of cancer and STAT1 may function as a tumor suppressor or oncoprotein in a cell-type specific manner." (PMID 25355139, 2014). "Moreover, the presence of tumor STAT1 activity correlated with disease progression from ductal carcinoma in situ to invasive carcinoma." (PMID 24725474, 2014). "We consistently found that treating NB4 cells with butyrate causes a significant downregulation of the mRNA levels of HLA-A and HLA-B. Truly, the cellular context may determine whether STAT1 acts as tumor promoter or as a tumor suppressor." (PMID 24810717, 2014). "Interestingly, the upregulation of MHC class I molecules which is promoted by STAT1, represents a general mechanism how leukemic cells can escape tumor surveillance by natural killer cells in mice." (PMID 24810717, 2014). "The question arises whether this interaction is restricted to the tumor or may also reflect a systemic response which can be monitored by analysis of serum samples of patients for elevated levels of proteins induced by STAT1." (PMID 24725474, 2014). "Fibroblasts failed to inhibit growth of STAT1-deficient tumor cells, confirming a crucial role of STAT1 for the crosstalk between tumor cells and fibroblasts." (PMID 24818101, 2014). "The other genes exhibited no selective association with expression of STAT1 in one of the tumor compartments." (PMID 24725474, 2014). "First, we tested whether activation of 18Co cells with TNF, or with LPS, a known inducer of inflammatory mediators, alters their ability to activate STAT1 activity and their crosstalk with tumor cells." (PMID 24818101, 2014). "To conclude, our findings suggest that STAT1 is a tumor suppressor in ESCC." (PMID 25355139, 2014). "Furthermore, STAT1 expression was also found to correlate with the depth of tumor invasion and tumor size." (PMID 25355139, 2014). "In contrast, STAT1 has a tumor-promoting function in leukemogenesis and progressed melanoma." (PMID 24489749, 2014). "A previous study also reported that Stat1 functionally promoted apoptosis and tumour suppression." (PMID 24821075, 2014). "This indicates that either tumor cells with high STAT1 expression are more likely to provide a favorable environment for the recruitment/expansion of macrophages in the tumor or that macrophages promote an environment leading to high STAT1 expression in the tumor." (PMID 24725474, 2014).
tumor (continued). "In conclusion, our findings suggest that STAT1 is a tumor suppressor in ESCC." (PMID 25355139, 2014). "We showed that fibroblasts secrete a number of soluble factors, but it is currently unknown which of these factors is responsible for the activation of STAT1 in tumor cells." (PMID 24818101, 2014). "Forced over-expression of STAT1 in tumor cells was found to confer resistance to radiotherapy and tumor cells with an increased propensity to metastasize to the lung after serial transplantations were shown to acquire a phenotype characterized by high expression levels of STAT1." (PMID 24725474, 2014). "It has been postulated from these observations that tumors may adapt to the anti-tumor action of STAT1 by down-regulating its expression and/or by impairing its activation." (PMID 24725474, 2014). "In addition to its function in immune cells, expression of STAT1 in the tumor epithelium has been shown to exert an inhibitory effect on the development of the tumor." (PMID 24725474, 2014). "Overall, these observations suggest that STAT1 carries tumor suppressor functions." (PMID 25355139, 2014). "There is also evidence that STAT1 carries tumor suppressor functions." (PMID 25355139, 2014). "It has been proposed that high expression of STAT1 in established tumors could be the result of a selection process and promote the escape of tumor cells from IFN-γ-mediated tumor surveillance." (PMID 24725474, 2014). "In order to find out whether JAK-STAT signalling was also compromised by hypoxia in the analysed tumour and native cell models the amount of STAT1 protein was determined via immunoblotting." (PMID 23675474, 2013). "Both STAT-1 and STAT-3 signaling have been implicated in tumor development." (PMID 24216992, 2013). "STAT1 is considered to play mutually exclusive roles in tumor cells." (PMID 23741352, 2013). "Interestingly, Stat1-positive tumor cells in residual tumors displayed significantly less DNA damage than Stat1-negative tumor cells." (PMID 23520493, 2013). "The increased DNA repair activity of Stat1-positive tumor cells may have primed tumor cells for drug tolerance and tumor relapse after chemotherapy in this model." (PMID 23520493, 2013). "IFN-у/STAT1 signaling can induce cell cycle arrest, apoptosis and anti-tumor immunity." (PMID 24058673, 2013). "Mice lacking or deficient in IFNG receptors or STAT1 developed tumors more rapidly, and had a higher tumor frequency than wild type mice following a challenge with methylcholanthrene." (PMID 24244422, 2013). "Regarding this issue, STAT1 overexpression is associated with IFN resistance in SCC cells and a third-generation bisphosphonate, YM529 which has almost equivalent antitumor effect to ZOL, augmented tumor-suppressive effects of IFN on RCC cells." (PMID 23741352, 2013). "Ipilimumab may also rescue tumor-impaired IFN-γ pathways in CD4+ T cells, since a number of genes associated with IFN-γ signals such as STAT1, ISG15, GBp1, and EIF2AK2 were up-regulated by ipilimumab (data not shown)." (PMID 22788688, 2012). "Our findings thus demonstrate that the tumor suppressor function of STAT1 is cell-autonomous." (PMID 22264274, 2012). "In this report, we show that E2F1 and STAT1 are activators of MUC4 mucin tumor marker." (PMID 22537161, 2012). "Cells lacking STAT1 respond aberrantly to IFNα/β and IFNγ, and STAT1-/- mice display immune defects rendering them highly susceptible to infection and tumor development." (PMID 22264274, 2012). "Since Stat1 and Stat3 show opposing patterns that promote or inhibit apoptosis, respectively, we examined the expression of anti-apoptotic Bcl-XL and pro-apoptotic pBad and Bax proteins in AT-101 sensitized tumor cells in the presence of ATC or aATC." (PMID 23185240, 2012).
tumor (continued). "It has been hypothesized that constitutive activation of STAT1 promotes a “switch” from a cytotoxic signaling pathway to a pro-tumor survival phenotype." (PMID 22242177, 2012). "Epithelial-specific deletion of STAT1 accelerates tumor development in the ErbB2/Neu tumor model." (PMID 22264274, 2012). "In addition to inhibiting proliferation and survival, IFN-γ enhances the immunogenicity of tumor cells, in part, by enhancing the STAT1-dependent expression of MHC proteins." (PMID 22608253, 2012). "However, several reports have demonstrated that prolonged IFN signaling or constitutive STAT1 signaling promotes not only tumor growth, but also resistance to chemotherapy and radiation." (PMID 22242177, 2012). "STAT1 also has a tumor suppressive role in mammary epithelium in ERBB2/neu-induced breast cancer." (PMID 22295238, 2011). "Activation of the transcription factors STAT1/STAT3 is crucial in determining whether inflammation in the tumor microenvironment promotes or inhibits cancer development." (PMID 21931823, 2011). "STAT1's tumor suppressing properties may be related to cell-intrinsic effects as STAT1 has been shown to block proliferation and to be involved in the induction of apoptosis." (PMID 22185785, 2011). "However, STAT1 is the major effector of IFNγ, which is antiproliferative or tumoricidal in several cancer cell types; although STAT3-decoy ODN has been found to induce tumor cell death in several different cell systems, it can also inhibit STAT1." (PMID 21486470, 2011). "For the reciprocal regulation of STAT1/3 activity, STAT3 inhibition by JAK/STAT antagonist AG490 may allow STAT1 activation and the expression of antitumor cytokines to suppress tumor metastasis." (PMID 21931823, 2011). "Additionally, STAT1 exerts an intrinsic tumor suppressing role by controlling and blocking proliferation of the mammary epithelium." (PMID 22185785, 2011). "Inhibiting STAT3 by AG490 induces anti-tumor activity via activation of STAT1 and autophagy." (PMID 21931823, 2011). "The mathematical model not only reproduced the experimental data, but also underscored the conclusions drawn from the experiments by indicating that a maximum of 1/500 of total STAT1 is located as phosphorylated STAT1 in the nucleus upon IFNγ treatment of the tumor cells." (PMID 21310022, 2011). "Prophylactic intervention reversed tumor-suppressed phosphorylation or expression of STAT1 (1.82±0.20 vs. 0.46±0.10, p<0.001) and SOCS1 and suppressed the tumor-induced phosphorylation or expression of STAT3 (0.72±0.24 vs. 3.74±1.07, p<0.05) and SOCS3 in the lung tissues." (PMID 21931823, 2011). "Additionally, STAT1 acts to prevent proliferation and promote apoptosis, but in some tumor cells, STAT1 plays a prosurvival role." (PMID 20737505, 2010). "Surprisingly, Stat1 gene inactivation also partially reduces gastric tumourigenesis in gp130Y757F mice, despite its general function in mediating IFNγ-dependent anti-tumour immunity." (PMID 20478049, 2010). "As a consequence, STAT1 knock-out mice develop tumours more rapidly." (PMID 20738848, 2010). "In contrast, emerging data reveal that in certain cellular contexts the IFN/STAT1 pathway may mediate tumor cell growth." (PMID 19503789, 2009). "A comparison of irradiated STAT1 WT and KD tumours demonstrated even larger differences." (PMID 19891767, 2009).
tumor (continued). "In addition, three subunits of the soluble catalytic core of mitochondrial adenosine triphosphate (ATP) synthase (ATP5A1, ATP5B and ATP5O) were up-regulated in STAT1 WT relative to KD tumours." (PMID 19891767, 2009). "Indeed, KD of STAT1 in untreated tumours led to a significant (t-test; P = 0.050) 2.7-fold suppression of tumour volume at day 40 relative to STAT1 WT tumours." (PMID 19891767, 2009). "In this regard, we asked whether overexpression of the IFN/STAT1 pathway provides such a selective advantage to tumor cells, thereby leading to improved lung colonization." (PMID 19503789, 2009). "Importantly, the STAT1 pathway was significantly (t-test; P = 7.44e-5) up-regulated 3.8-fold in STAT1 WT relative to KD tumours." (PMID 19891767, 2009). "Taken together these results suggest that STAT1 plays an important role in the lung colonization ability of B16F1 clones and derivatives and that STAT1 provides a molecular link between colonization propensity and resistance of metastatic tumor clones to cytotoxic stimuli." (PMID 19503789, 2009). "The STAT1-dependent expression of glycolysis was particularly evident, as 16 enzymes in this pathway were identified in our analysis, with the majority of them up-regulated in STAT1 WT relative to KD tumours." (PMID 19891767, 2009). "Conversely, proteins hypophosphorylated (Tumor/Normal phosphorylation spectral count ratio >1) in tumors include the transcription factors STAT1 and STAT5, the protein tyrosine phosphatase PTPN11, the G-protein coupled receptor GPRC5A, and the kinases MAPK1, MAPK3, and TNK2." (PMID 19946374, 2009). "New therapies targeted against the IFN/STAT1 signaling pathway may provide an effective strategy to treat or sensitize aggressive tumor clones to conventional cancer therapies and potentially prevent distant organ colonization." (PMID 19503789, 2009). "We tested the hypothesis that tumor clones overexpressing the IFN/STAT1 pathway (STAT1H) exhibit an increase in lung colonization compared to cells that do not overexpress this pathway (STAT1L)." (PMID 19503789, 2009). "Our results are consistent with Warburg's finding that tumour cells utilize glycolysis as the main pathway of energy metabolism even in the presence of oxygen and suggest that STAT1 is involved in the transcriptional regulation of the Warburg effect in tumour cells." (PMID 19891767, 2009). "Therefore, the IFN/STAT1 pathway represents a signaling pathway that mediates crosstalk between the host microenvironmental components and the tumor cells." (PMID 19503789, 2009). "On the other hand, the interferon and STAT1 metagenes are also correlated (R2 = 0.52), which might represent an interferon response of tumor cells or other cell types in the respective samples." (PMID 19272155, 2009). "Analysis of the differences in gene expression between cells from differentially selected tumours demonstrated up-regulation of the genes in the Signal Transducer and Activator of Transcription 1 (Stat1) signalling pathway in radioresistant nu61 tumours compared with radiosensitive SCC61 tumours." (PMID 19437244, 2009). "However, recent findings showed that the anti-tumor function of Stat1 is determined by the type of the tumor and the oncogenic signalling within it." (PMID 18941537, 2008). "Given that p27Kip1 plays an important role in cell motility independent of its cell cycle regulatory functions, regulation of p27Kip1 levels by Stat1 may also have profound roles in cell migration and tumor metastasis." (PMID 18941537, 2008). "The suppression of the genes EGR1 and STAT1 correlates with active tumor formation." (PMID 18811983, 2008). "Even though we do observe slight increases in serine 727 STAT1 phosphorylation with flavonoid treatment alone, it is likely that this phenomenon is related to these compounds' pro-apoptotic effects evidenced in tumor cell lines." (PMID 18817573, 2008). "Increased expression of STAT1 triggers tumor progression and leads to down-regulation of apoptosis." (PMID 16001973, 2005).
tumor (continued). "Although STAT1 activation has been reported in some tumours and cell lines, STAT1 activation is associated with tumour suppression rather than proliferation in most conditions." (PMID 12865928, 2003). "Thus, we have identified a previously unknown APC/PTPN13/STAT1-dependent tumor immune-suppressive mechanism." (PMID 41486293, 2026). "In addition, STAT1 expression in macrophages identified patients with improved survival and an intact tumor immune system, who may benefit from immunotherapy." (PMID 41522359, 2026). "The inverse relationship between STAT1, a central mediator of IFNα-induced Th1 and pro-apoptotic signalling, and IL-13, a Th2 cytokine involved in immunoregulation and profibrotic megakaryopoiesis, suggests a shift in immune tone towards anti-tumour responses and clonal suppression." (PMID 40723157, 2025). "However, USP5 deficiency did not affect IFN-I response in tumor cells because neither p-STAT1 and p-STAT2 levels nor IFN-stimulated gene expression were changed in USP5-depleted cells." (PMID 41321309, 2025). "Furthermore, STAT1 is generally recognized as a tumor suppressor." (PMID 40141028, 2025). "We found that the expression levels of p‐STING, p‐TBK1, p‐IRF3, and p‐STAT1 were markedly increased in the Rfwd3 knockdown group compared to the shNC group, indicating that knocking down Rfwd3 in tumor cells results in activation of the STING pathway in adjacent immune cells." (PMID 41117130, 2025). "Together, these results identify Lys637 acetylation as a previously unknown regulatory modification that compromises STAT1 function by preventing proper homodimerization, thereby reducing its transcriptional activity and ultimately blunting tumor cell response to IFN-γ in cetuximab-resistant HNSCC." (PMID 41205596, 2025). "In addition, ATM inhibition could reverse the immune “cold phenotype” of tumor cells by activating the TNF-α/STAT1 signaling pathway and up-regulating the expression of MHC-I molecules." (PMID 40825766, 2025). "Moreover, STAT1 has also been shown to negatively regulate pro-angiogenic molecules like bFGF, significantly inhibiting tumorigenicity, angiogenesis, and metastasis, thereby serving as a negative regulator of tumor growth and metastasis." (PMID 39900908, 2025). "In addition, K562 tumor cells had moderate resistance to the killing of Vγ9Vδ2-T cells in the presence of rhIFNγ and inhibition of STAT1 activation and NO synthesis by fludarabine or 1400 W alleviated the dampened cytotoxic capacity of Vγ9Vδ2-T cells prompted by rhIFNγ." (PMID 40603316, 2025). "Additionally, low-dose inhibition of STAT1/ETS1 combined with immune checkpoint blockade could synergistically enhance anti-tumor efficacy while minimizing adverse effects." (PMID 40948762, 2025). "Mechanistically, complement activation can promote immunosuppressive tumor-associated macrophage (TAM) polarization, angiogenesis, and metastasis through various pathways-including the NFAT1-C3a-C3aR feedback loop and the JNK/STAT1 axis mediated by platelet-TAM interactions." (PMID 41179292, 2025). "Thus, ALK5i enhances IRF and STAT1 gene expression, and enhances anti-tumor immune responses." (PMID 38516270, 2024). "Thus, CGA might inhibit PD-L1 expression in tumor cells via suppression on the STAT1 phosphorylation-IRF1-PD-L1 pathway." (PMID 38164171, 2024). "Thus, we proposed that the STAT1-IFITM3 feedback loop could be a potential target when designing Treg-specific anti-tumor therapies." (PMID 38167862, 2024). "Implicating ferroptosis inducers that stimulate STAT1 activation may overcome tumor resistance to immunotherapy, providing a wide range of potential for the clinical implementation of ferroptosis inducers in combination with immune checkpoint inhibitors (ICIs)." (PMID 39015566, 2024).